IRF5 (interferon regulatory factor 5)
Diseases named in the same sentence as IRF5 in open-access papers (continued):
Sharing a sentence is not in itself a finding about the gene and the disease.
anterior uveitis (1 paper, 2013). Inflammation of the iris and anterior chamber of the eye. "In conclusion, we show for a first time that two genetic variants within the IRF5 region influence the macular edema development in patients with non-anterior uveitis." (PMID 24116155, 2013). "Our results clearly showed for the first time that two functional genetic variants of IRF5 may play a role in the development of macular edema in non-anterior uveitis patients." (PMID 24116155, 2013). "Three IRF5 polymorphisms, rs2004640, rs2070197 and rs10954213, representative of each group, were genotyped using TaqMan® allelic discrimination assays in a total of 263 non-anterior uveitis patients and 724 healthy controls of Spanish origin." (PMID 24116155, 2013).
antiphospholipid syndrome (1 paper, 2019). A disorder caused by the presence of autoantibodies directed against phospholipids, causing a hypercoaguable state, which may result in blood clots, stroke, heart attack, and in women, significant pregnancy-related complications, including miscarriage and still birth. "Recent reports have confirmed the additive effects of STAT4 and IRF5 SNPs which may increase the risk of SLE and antiphospholipid syndrome." (PMID 31871930, 2019).
arteriosclerosis (1 paper, 2020). A vascular disorder characterized by thickening and hardening of the walls of the arteries. "We measured expression of TLR4, TIRAP, MyD88, TRAF6, p38, NEMO, and IRF5 to test the anti-arteriosclerosis effect of corilagin." (PMID 32849545, 2020).
atopic asthma (1 paper, 2025). An asthma that is characterized by symptoms that are triggered by an allergic reaction caused by inhaled allergens such as dust mite allergen, pet dander, pollen and mold. "In an atopic asthma model, IRF5 reduces lung hyperresponsiveness, mucus production, and IL13." (PMID 41516283, 2025).
bladder cancer (1 paper, 2023). "IRF5 (p=0.055), CCN1 (p=4.1e-08), MYC (p=0.039), POU5F1 (p=0.027), and TGFB1I1 (p=6.5e-08) were significantly differentially expressed at different stages of bladder cancer." (PMID 37433010, 2023). "Similarly, in TCGA database bladder cancer samples, CCN1 (p=7.9e-07), MYC (p=0.0043), POU5F1 (p=0.021), and TGFB1I1 (p=6.0e-05) had significant differences in bladder cancer high-grade and low-grade samples, in addition to IRF5 (p=0.2)." (PMID 37433010, 2023).
carotid atherosclerosis (1 paper, 2022). A thickening and loss of elasticity of the walls of carotid arteries that occur with formation of atherosclerotic plaques. "To explore if CD11c expression was associated with IRF5 in human carotid atherosclerosis we sought to identify whether IRF5 gene expression and plaque area correlated with CD11c gene expression." (PMID 35567557, 2022).
chlamydial infection (1 paper, 2017). "Using CRISPR/Cas9 technology, we generated biallelic knockout mutations in host genes encoding IRF5 and IL-10RA in iPSCs, and confirmed their roles in limiting chlamydial infection in macrophages." (PMID 28440293, 2017).
chronic kidney disease (1 paper, 2023). Impairment of the renal function secondary to chronic kidney damage persisting for three or more months. "We study whether allelic variations in IRF5 are associated with the incidence of chronic kidney disease (CKD) in a general population." (PMID 37978231, 2023).
chronic myeloid leukaemia (1 paper, 2021). "Previously, phosphorylation on site Tyr-104 (human/mouse) by BCR-ABL kinase in chronic myeloid leukaemia cells has been linked to negative regulation of IRF5 transcriptional activity." (PMID 34795257, 2021).
chronic obstructive pulmonary disease (1 paper, 2026). A chronic and progressive lung disorder characterized by the loss of elasticity of the bronchial tree and the air sacs, destruction of the air sacs wall, thickening of the bronchial wall, and mucous accumulation in the bronchial tree. "Targeting IRF5 may be a potential therapeutic strategy for chronic obstructive pulmonary disease." (PMID 41639423, 2026). "Interferon regulatory factor 5 (IRF5) is a key regulator of inflammatory responses; however, its role in chronic obstructive pulmonary disease remains unknown." (PMID 41639423, 2026).
Cognitive impairment (1 paper, 2021). Abnormal cognition is characterized by deficits in thinking, reasoning, or remembering. "Rats with intracerebroventricular injection of β-amyloid resulted in cognitive impairment and imbalance between IRF4 and IRF5, which was rescued by M2 macrophage transplantation." (PMID 34857756, 2021).
colon adenocarcinoma (1 paper, 2015). "Indeed, previous studies in breast and colon adenocarcinoma models, amongst other cell types, indicate that IRF5 proteins reside in the cytoplasm of unstimulated cells." (PMID 25649192, 2015).
demyelination (1 paper, 2025). "To confirm that IRF5 is essential for remyelination, as suggested by our EAE data, we employed a chemically induced demyelination model." (PMID 40137979, 2025).
endotoxemia (1 paper, 2019). "In addition, endotoxemia resulted in the upregulation of multiple interferon-inducible genes such as an interferon-induced protein with tetratricopeptide Repeats (Ifit1-3), MX Dynamin Like GTPase 1 (Mx1) and Interferon regulatory element 5 (Irf5)." (PMID 32038494, 2019).
fibroblast disease (1 paper, 2019). "Our results combined with these reports suggest that additional studies are needed to confirm the role of IRF5 in the SSc dermal fibroblast disease phenotypes using non-viral inhibitor strategies." (PMID 30872777, 2019).
Flavivirus Infections (1 paper, 2021). Infections with viruses of the genus FLAVIVIRUS, family FLAVIVIRIDAE. "In particular, the critical contribution of IFN-I signal and transcription factors (IRF3, IRF5, IRF7, IPS-1, etc.)for IFN-I production to the control of in vivo flavivirus infection mostly focused on WNV has been described." (PMID 34130738, 2021). "Indeed, the critical role of IFN-I and its transcription factors (IRF3, IRF5, and IRF7) has been described in flavivirus infection in vivo including WNV and DenV, but not JEV." (PMID 34130738, 2021).
gout (1 paper, 2025). A condition characterized by painful swelling of the joints, which is caused by deposition of urate crystals. "A recent genome-wide association study (GWAS) has identified rs4728141 as a lead SNP associated with gout in the European population and included IRF5 as a high priority gene for involvement in gout." (PMID 41155224, 2025). "Furthermore, the rs4728141 polymorphism C allele was associated with both increased IRF5 expression and susceptibility to gout." (PMID 41155224, 2025). "IRF5 was one of the top candidate genes, with rs4728141 as the lead SNP at the gout GWAS identified locus in the European population." (PMID 41155224, 2025). "Interferon Regulatory Factor 5 plays an important role in the regulation of innate immune responses by amplifying the Nuclear Factor κB response, which is critical in gout inflammation." (PMID 41155224, 2025). "The IRF5 SNP is associated with significantly enhanced synergistic cytokine production in response to palmitate and MSU crystals, particularly in the gout subgroup, strongly indicating that this variant modulates cytokine production specifically in gout-relevant context." (PMID 41155224, 2025). "Although IRF5 was not thoroughly investigated in the context of gout, its established proinflammatory role in other autoimmune and inflammatory diseases suggests that heightened IRF5 activity could contribute to increased risk and severity of gout." (PMID 41155224, 2025).
Hypercholesterolemia (1 paper, 2017). An increased concentration of cholesterol in the blood. "Our data demonstrate that IRF5 deficiency in mice with hypercholesterolemia reduces both the intralesional necrotic area and CD11c+ myeloid cell content." (PMID 28698173, 2017). "Next, we explored the mechanistic relationship between these 2 observations by investigating whether IRF5 deficiency affected the functional behavior of myeloid cells in mice with hypercholesterolemia." (PMID 28698173, 2017).
idiopathic inflammatory myopathies (1 paper, 2014). "Single-nucleotide polymorphisms (SNPs) in the TNFAIP3, IFIH1, and IRF5 genes have been associated with several auto-inflammation diseases, while the susceptibility between these genes and idiopathic inflammatory myopathies (IIMs) were not reported." (PMID 25337792, 2014).
IgA nephropathy (1 paper, 2010). "Thus, one might speculate that susceptibility to IgA nephropathy may be due to common variations in IRF5, TRAF1-C5 and STAT4 genes." (PMID 20479942, 2010).
immune deficiencies (1 paper, 2024). "Numerous genes have been implicated in the pathogenesis of SLE, particularly components of the interferon pathways such as IRF5, STAT4, and SPP1, which likely reflect intrinsic immune deficiencies in SLE patients." (PMID 39194726, 2024).
intestinal inflammation (1 paper, 2021). "IRF5 activity in mononuclear phagocytes (MNPs) plays a critical role in the pathogenesis of intestinal inflammation and that mice deficient in IRF5 are protected from overblown colitis." (PMID 34795257, 2021).
keloid (1 paper, 2021). An irregularly shaped, elevated mark on the skin caused by deposits of excessive amounts of collagen during wound healing. "Besides, the overexpression of miR-133a-3p can suppress fibrosis by down-regulating IRF5 and then inhibiting the TGF-β/Smad2 signaling pathway, therefore, promoting apoptosis and reducing the proliferation in keloid fibroblasts." (PMID 34225723, 2021).
latent infection (1 paper, 2021). "In addition, latent infection of EBV influences the alternative splicing of interferon regulatory factor 5 (IRF5)." (PMID 33530521, 2021).
Leigh syndrome (1 paper, 2025). A progressive neurological disease defined by specific neuropathological features associating brainstem and basal ganglia lesions. "Moreover, some of the genes that were downregulated in the absence of IRF-5, like Ndufaf3 and Coq4, are associated with mitochondrial disorders in humans and with the Leigh syndrome." (PMID 40494997, 2025).
lentivirus infection (1 paper, 2024). Virus diseases caused by the Lentivirus genus. "Macrophages overexpressing IRF5 were obtained through lentivirus infection." (PMID 39623605, 2024).
Li-Fraumeni syndrome (1 paper, 2011). "A similar study in immortalized cell lines from patients with Li-Fraumeni syndrome that had decreased IRF5 expression showed no detectable methylation of CpG islands in the IRF5 promoter." (PMID 22053985, 2011).
liver failure (1 paper, 2024). A liver disease characterized by the liver losing or has lost all of its function. "Therefore, IRF5 may be one of the therapeutic targets for treating acute fulminant liver failure caused by E11 in newborns." (PMID 39045132, 2024).
lung disease (1 paper, 2025). "IRF5 shows one of the strongest associations with SSc; certain IRF5 SNPs correlate with disease severity and survival, with higher IRF5 expression linked to worse lung disease." (PMID 41009491, 2025).
macrophage activation syndrome (1 paper, 2012). A complication of rheumatic disease that is caused by excessive activation and uncontrolled proliferation of T lymphocytes and well-differentiated macrophages. "It has been postulated that a genetic association between sJIA and macrophage activation syndrome (MAS) exists via a mutated perforin gene (PRF1) and polymorphism of both MUNC13-4 and interferon regulatory factor 5 (IRF5) genes." (PMID 22235382, 2012).
macular edema (1 paper, 2013). "Elevated levels of intraocular IL-6 and TNF-α, whose expression is upregulated by IRF5, have been reported in patients with intermediate uveitis, especially in those with macular edema." (PMID 24116155, 2013). "This analysis also showed a phenotype-specific association of IRF5 with the absence of macular edema but not with the global disease (data not shown)." (PMID 24116155, 2013). "Different allelic combinations of the IRF5 genomic region according to the presence/absence of macular edema in uveitis patients." (PMID 24116155, 2013).
malaria (1 paper, 2025). Malaria is a serious and sometimes fatal disease caused by a parasite that commonly infects a certain type of mosquito which feeds on humans. "Real time PCR was used to quantify the relative expression of STAT-1 and IRF-5, critical transcription factors for M1 polarization, and STAT-6 and c-Maf, salient factors for M2 polarization, in placental macrophages, and compared between malaria positive and negative women." (PMID 40007543, 2025).
metastatic disease (1 paper, 2024). "Given the clear association of loss of IRF5 expression with worsened prognosis and increased metastasis of BC, we aimed to explore this association in another tumor type with similar devastating effects from metastatic disease." (PMID 38969706, 2024). "Further, findings from the current study support the concept that IRF5 mRNA within a t-dEV may be a biomarker of less metastatic disease and define a pathway to inhibit metastasis." (PMID 38969706, 2024).
monocytopenia (1 paper, 2020). "When projecting IRF5 expression over the t‐SNE maps, we confirm monocyte‐specific expression, maintained at a high level despite marked monocytopenia in severe COVID‐19 with T2D." (PMID 32816392, 2020).
Newcastle disease (1 paper, 2013). A condition caused by infection by the Newcastle disease virus, which may be characterized by conjunctivitis, respiratory illness, and diarrhea. "The 1A promoter was activated by herpes simplex, Newcastle disease and vesicular stomatitis viruses in PBMCs, Daudi, and THP-1 cells; respectively; as evidenced by increased transcription of IRF5." (PMID 24223576, 2013).
pancreatitis (1 paper, 2018). Inflammation of the pancreas. "Likewise, in the severe acute pancreatitis mouse model there is pancreatitis-induced activation of lung M1 macrophages with high expression of IRF5, TNFα, iNOS and IL10." (PMID 30515152, 2018). "Moreover, in vivo, treatment with IRF5 siRNA reversed the pancreatitis-induced activation of lung macrophages from M1 phenotype to M2 phenotype." (PMID 30515152, 2018).
pemphigus (1 paper, 2019). Pemphigus is a group of rare autoimmune diseases that cause blistering of the skin and mucous membranes (mouth, nose, throat, eyes, and genitals).This conditioncan occur at any age, but often strikes people in middle or older age. "Overall, this study showed that self-reactive and non-self-reactive B cell populations from pemphigus patients do not express the same genes during the acute phase of the disease, in particular genes encoding for IL-1β, IL-12p35, IL-23p19, and IRF5." (PMID 31440235, 2019).
peritonitis (1 paper, 2017). Inflammation of the peritoneum (tissue that lines the abdominal wall and covers most of the organs in the abdomen). "This study showed that MS19, an AAAG-rich ODN, displayed an immune regulatory role in interfering IRF5 on a septic peritonitis model mice infected by E. coli, and reduced the inflammatory response induced by elevated pro-inflammatory cytokines." (PMID 28492513, 2017).
polycystic kidney disease (1 paper, 2024). A usually autosomal dominant and less frequently autosomal recessive genetic disorder characterized by the presence of numerous cysts in the kidneys leading to end-stage renal failure. "IRF5 significantly influences the progression of polycystic kidney disease (PKD) by enhancing inflammatory cytokine production in resident macrophages, a key factor in accelerating cystogenesis." (PMID 38892221, 2024).
Renal cyst (1 paper, 2023). A fluid filled sac in the kidney. "Interferon regulatory factor-5 (IRF5) is a transcription factor associated with renal cyst-promoting cytokines in macrophages." (PMID 36675597, 2023).
renal cystic disease (1 paper, 2023). "An injection of the IRF5 antisense oligonucleotide into CKO mice reduced the number of macrophages, IRF5 expression in the identified macrophages, and renal cystic disease severity." (PMID 36675597, 2023).
sarcoma (1 paper, 2023). A usually aggressive malignant neoplasm of the soft tissue or bone. "Multiple genes were downregulated (p < 0.05) in sarcoma tumors, including HSP90AB1, IGHA1, INSM1, IRF5, MAP2K2, and SEH1L." (PMID 37445737, 2023).
skin inflammation (1 paper, 2020). "Although IRF5 is known to play a critical role in the induction of proinflammatory cytokines by immune cells, such as dendritic cells (DCs), macrophages, and monocytes, IRF5 deficiency unexpectedly exacerbated psoriasiform skin inflammation." (PMID 32456211, 2020). "In addition, the decreased IL-10 mRNA expression levels were also detected in the IRF5 KO mice and thought to be associated with the exacerbation of skin inflammation." (PMID 32456211, 2020). "Worse dermatitis with more severe scales was detected in IRF5 KO mice by imiquimod application compared to the WT mice." (PMID 32456211, 2020). "Considering our results, amplified Th17 responses could have a stronger influence on the development of imiquimod-induced skin inflammation than a decrease in TNF-α and IL-6 in IRF5 KO mice." (PMID 32456211, 2020).
steatosis (1 paper, 2026). Increased lipid within the cytoplasm of cells. "Additional evidence demonstrates that IRF5, IRF6, and IRF8 are also play key roles in hepatocytes: IRF5 mediates Fas-induced apoptosis, IRF6 suppresses PPARγ to reduce lipid accumulation, and IRF8 aggravates steatosis through a BMAL1/PPARγ axis." (PMID 41614922, 2026).
stomach adenocarcinoma (1 paper, 2021). "PLXNC1, regulated by IRF5, is an immune-related gene that was significantly associated with M2 macrophages and poor outcome in stomach adenocarcinoma." (PMID 34277610, 2021).
thyroid (1 paper, 2012). "In summary, the present study indicates that IRF5 favors the thyroid tumoral phenotype." (PMID 22507190, 2012).
triple-negative breast carcinoma (1 paper, 2025). An invasive breast carcinoma which is negative for expression of estrogen receptor (ER), progesterone receptor (PR), and human epidermal growth factor receptor 2 (HER2). "However, the precise mechanisms underlying IRF5’s role in triple-negative breast cancer remain unclear and warrant further investigation." (PMID 41179282, 2025). "To clarify the molecular mechanisms by which IRF5 mediates metabolic reprogramming in triple-negative breast cancer (TNBC), we conducted differential gene ranking analysis between groups with high and low IRF5 expression." (PMID 41179282, 2025).
uveitis (1 paper, 2013). An inflammatory process affecting a part of or the entire uvea. "Genotype and minor allele frequencies of IRF5 genetic variants in uveitis patients and healthy controls." (PMID 24116155, 2013). "The aim of our study was to analyze three SNPs, representative of each group of variants independently associated with SLE, in order to explore the role of IRF5 in uveitis susceptibility and its clinical subgroups." (PMID 24116155, 2013). "In the current study we aimed to evaluate whether three sets of correlated IRF5 genetic variants, independently associated with SLE and with different functional roles, are involved in uveitis susceptibility and its clinical subphenotypes." (PMID 24116155, 2013).
ventricular dilatation (1 paper, 2015). "The authors suggest that since si-IRF5 was only administrated during the first five days post-AMI, the difference in post-AMI ventricular dilatation development is most likely the result of improved infarct healing in si-IRF5-treated mice." (PMID 26690421, 2015).